CGAS (cyclic GMP-AMP synthase)
Diseases named in the same sentence as CGAS in open-access papers (continued):
Sharing a sentence is not in itself a finding about the gene and the disease.
infection (continued). "Cytoplasmic Mn2+ also triggers cGAS to synthesize cGAMP independent of dsDNA by a novel catalytic mode, initiating type I-IFN response and cytokine production without any infection." (PMID 35803579, 2022). "At 36-h post-infection, cells were treated with or without protein synthesis inhibitor (CHX, 100 μg/ml), then the level of cGAS protein was determined by Western blotting." (PMID 34394047, 2021). "Although this would be consistent with the mtDNA-dependent cGAS-stimulation, the reported activation of cGAS during apoptosis also depended on Bax/Bak, but Bax/Bak were not required for STING-mediated cytokine-secretion in MVA-infection." (PMID 34711816, 2021). "We have previously shown that cGAS, which is required for optimal IFN-I production after ECTV infection, is not necessary in parenchymal cells (including hepatocytes) for resistance to mousepox." (PMID 34015056, 2021). "However, it was found that the cGAS ortholog in Drosophila did not play a role during Listeria or IIV6 infection, which was speculated to be ascribed to the lack of the zinc-ribbon domain and a positively charged N terminus functionally important for DNA binding." (PMID 34168656, 2021). "Inactivating cGAS or STING in monocyte-derived dendritic cells and macrophages reduces IFN-β secretion after infection with DNA viruses (HCMV and VACV) but not with an RNA virus (VSV)." (PMID 34372578, 2021). "In contrast, robust phosphorylation of IRF3 was not evident at any time point post-infection with HPV, indicating that the cGAS/STING pathway was not able to sense and respond to encapsidated vDNA." (PMID 33253291, 2020). "In this infection model, IFN production was induced by the DNA sensing cGAS-STING pathway rather than by MDA5/RIG-I, and preceded PKR activation and SG formation, indicating that SGs are dispensable for cGAS-mediated IFN production upon HSV-1 infection." (PMID 32899736, 2020). "In agreement with our previous observations, ECTVΔvSlfn or ECTV-vSlfnΔp26 infection triggered high levels of IRF3 phosphorylation and these were abolished in the absence of cGAS and STING, but not MAVS." (PMID 32948585, 2020). "This STING-dependent response was also observed during infection with non-murine retroviruses such as HIV and demonstrated that cGAS is a common sensor of retroviral DNA." (PMID 32751803, 2020). "While STING was originally shown to activate not only IRF3 but also IRF7 and IRF3 and IRF7 have been shown to have non-redundant roles in different infection models, IRF3 is generally described in reviews as the main IRF downstream of cGAS and STING." (PMID 31877196, 2019). "Upon stimulation with polyinosinic–polycytidylic acid (poly(I:C)) or infection with the Sendai virus, a dsRNA analog and an RNA virus, respectively, IFN-β induction was not affected in the absence of cGAS or STING." (PMID 30241345, 2018). "Interestingly, infection with either of the three RNA viruses induced elevated levels of STING dimers in the lysates, and consistent with this, the residual induction of interferon-β and CXCL10 expression by IAV in MAVS-deficient cells was ablated when STING but not cGAS was knocked down by shRNA." (PMID 26893169, 2016). "Silencing of H2B, cGAS and STING inhibited IFN-β induction but not IL-1β secretion, and cGAMP activity is significantly reduced by H2B and IFI16 knockdown during infection." (PMID 27764250, 2016). "Notably, the activation of cGAS cannot be attributed to damage to the viral cores by PF74, as this compound was not used during the infection." (PMID 39623137, 2025). "Mn2+ itself is a potent cGAS activator that increases the sensitivity of the DNA sensor cGAS and its downstream junction protein STING, which induces cellular production of type I IFN and cytokines in the absence of any infection in vivo." (PMID 38817608, 2024).
infection (continued). "BX795, a TBK1 inhibitor, and RU.521, a cGAS inhibitor, did not inhibit the EV-D68-induced IFN-β production, demonstrating cGAS-STING-independent IFN-β production in response to EV-D68 infection." (PMID 39459875, 2024). "Hence, dysregulation of endogenous DNA can lead to aberrant cGAS-STING activation and produce a type I IFN response in the absence of infection." (PMID 37247757, 2023). "Collectively, using plasmid transfection, lentiviral transduction, and MVA∆E5R–E5-Flag infection approaches in several mammalian cell types, including HEK293T, MEFs, and BMDCs, we demonstrated interactions between E5 and cGAS, which is independent of DNA-binding." (PMID 37217469, 2023). "Interestingly, I267L inhibited transcription of IFNB1 gene induced by infection of SeV, whose RNA is sensed by RIG-I, but not by HSV-1, whose DNA is mostly sensed by cGAS." (PMID 35089988, 2022). "The infection activity of HSV-1, but not other viruses, reduced in the KO(LL/RK-NLS) cells, which is consistent with that only HSV-1 induces nuclear soluble cGAS." (PMID 35538147, 2022). "While the study of Lauterbach-Rivière concluded that in infected hepatocytes, HBV passively evades recognition by sensing its DNAs by cGAS/STING without active inhibition of the pathway, other studies have shown that infection by HBV suppresses components of the cGAS–STING pathway." (PMID 35458396, 2022). "Finally, we demonstrated that infection of HEK293T cells with SIVsm inhibited cGAS/STING-dependent NF-κB reporter activation, whilst infection with SIVsmΔvpx did not, despite equivalent levels of infection." (PMID 35073912, 2022). "In this context, the low expression of cGAS and STING in the hepatocytes may also explain the absence of quantifiable induction of IFN response upon infection." (PMID 33708225, 2021). "Furthermore, CXCL10 expression was not induced after infection of THP-1 cGAS knock out cells, consistent with CXCL10 induction being cGAS-dependent." (PMID 33300875, 2020). "Therefore we cannot exclude that upon infection, the levels of intracellular HBV DNA are not sufficient to activate the cGAS/STING pathway." (PMID 32485908, 2020). "We also found that deletion of signaling molecules that act upstream of type I IFN production including multiple TLRs, RIPK2, cGAS/STING, or MAVS pathways, did not increase BMDM fusion during infection while control BMDMs lacking MyD88 and TRIF or IFNAR1 extensively fused." (PMID 32150572, 2020). "Importantly, unlike wild‐type HIV‐1, infection with cleavage defective HIV‐1 triggered an IFN response in THP‐1 cells that was dependent on viral DNA and cGAS." (PMID 32852081, 2020). "Both IFNαR-/- and cGAS-/- mice displayed only a modest 2-fold increase in infectious VACV titer that, when compared to the 100,000 fold increase in titer in the 5 days since infection, was unlikely to explain the drastic change in pathology." (PMID 31603920, 2019). "Previous reports observed cGAS-STING activation and induction of NF-κB signaling pathways with subsequent expression of antiviral ISGs and inflammatory cytokines in primary human skin fibroblasts infected with MCPyV at late stages of infection, but not during the early stages of infection." (PMID 39110744, 2024). "In this study, we demonstrate that dephosphorylation of a catalytic serine residue of cGAS by the phosphatase PPP6C impairs its substrate binding and enzymatic activity, therefore provides a mechanism for keeping the DNA sensor cGAS inactive in the absence of infection to avoid autoimmune response." (PMID 32474700, 2020). "In addition, we showed that cGAMP, the cGAS-activated product mediating the activation of STING, was counteracted during Armenia/07 but not NH/P68 infection, suggesting that the viral mechanism displayed by Armenia/07 to inhibit STING activation somehow competes with cGAMP." (PMID 30918080, 2019).
infection (continued). "Furthermore, TRIM56(+) cGAS(−), TRIM56(−) cGAS(+), and TRIM56(−) cGAS(−) cells failed to induce IP-10 mRNA expression upon HSV-1ΔICP34.5 infection, whereas wild-type (WT) L929 cells were capable of inducing IP-10 mRNA expression upon HSV-1ΔICP34.5 infection." (PMID 29426904, 2018).
neurodegenerative disease (58 papers, 2020 to 2026). A disorder of the central nervous system characterized by gradual and progressive loss of neural tissue and neurologic function. "In neurodegenerative disease abnormal autophagy is associated with inability to recycle cellular components leading to accumulating DAMPs and chronic activation of the cGAS-STING innate immunity pathway and STING-mediated LC3 lipidation." (PMID 39156128, 2024). "The pathogenic role of cGAS/STING activation in neurodegenerative disease has been implicated by recent studies in animal models of PD." (PMID 36170200, 2022). "However, due to the distinctive molecular mechanisms underlying various neurodegenerative diseases, consequently, developing therapeutics targeting divergent upstream triggers or downstream effectors of cGAS-STING pathway is of critical importance." (PMID 38069505, 2023). "Gulenet al. found that mitochondria DNA (mtDNA) triggered a cGAS-dependent neuroinflammation in aged microglial, establishing a significant association between mitochondrial dysfunction and inflammation, both of which are hallmarks of ageing and neurodegenerative disease." (PMID 38069505, 2023). "Recent studies implicate dysregulated cGAS-STING signaling in neurodegenerative diseases and brain aging, with a prominent contribution to glial activation-associated neuroinflammation, a hallmark of many neurological disorders." (PMID 42222892, 2026). "In recent years, researchers at home and abroad have shown that activation of the microglia cGAS-STING pathway plays a wide range of roles in neurodegenerative diseases." (PMID 40918734, 2025). "The recognition of cGAS-STING pathway as an upstream axis related to chronic neuroinflammation indicates a deeper understanding in neurodegenerative disease." (PMID 41300248, 2025). "More and more studies have shown that the cGAS/STING/NLRP3 signaling pathway plays an important role in Neurodegenerative diseases." (PMID 40463371, 2025). "Emerging evidence further suggests that cGAS-STING activation is involved in the progression of several neurodegenerative diseases." (PMID 41300248, 2025). "The cGAS‐STING pathway is anticipated to emerge as a novel therapeutic target for the management of neurodegenerative diseases." (PMID 38459658, 2024). "cGAS/STING axis acts as a crucial signaling pathway in sterile inflammation– and age-associated degenerative diseases, in which it senses and responds to cytoDNA in a DNA sequence–independent, but DNA length–dependent, manner." (PMID 38488012, 2024). "There is increasing evidence that the cGAS-STING pathway is implicated in NLRP3-mediated neuroinflammation, contributing to neurodegenerative disease progression." (PMID 38481801, 2024). "In this section, we briefly outline the properties of selected active site cGAS inhibitors and their potential application as experimental compounds for mechanistic studies and therapies to treat neurodegenerative diseases." (PMID 37941028, 2023). "In our study, we investigated the abundance of cGAS-STING pathway components in neural cells with a build-up of protein aggregates in brain tissue from four human neurodegenerative diseases." (PMID 37239045, 2023). "Recent studies have shown that cGAS–STING signaling is involved in several neurodegenerative diseases, including Alzheimer’s." (PMID 37175853, 2023). "Overstimulation of the cGAS–STING pathway and its associated neuroinflammation is thought to be associated with the development or progression of various neurodegenerative diseases, including AD." (PMID 37175853, 2023). "The dysregulation of the innate immune cGAS–STING pathway and the associated neuroinflammation contribute to neurodegenerative diseases such as AD." (PMID 37175853, 2023). "Mounting recent studies implicate the important role of cGAS-STING signaling in the development of neurodegenerative diseases." (PMID 37433768, 2023).
neurodegenerative disease (continued). "Recently, aberrant or sustained cGAS/STING activation has been observed in a number of neurodegenerative diseases and is thought to contribute to neuronal dysfunction via microglial-induced CNS neuroinflammation and neurodegeneration." (PMID 37206668, 2023). "In summary, targeting the cGAS–STING pathway offers a novel therapeutic strategy for neurodegenerative diseases, while stimulating autophagy to eliminate senescent cells and activated STING can also be employed as a new treatment." (PMID 36618820, 2022). "While it is true that neurodegenerative diseases occur after aberrant activation of the cGAS-STING pathway, the role of this pathway in different neurological diseases is still needed to be further investigated." (PMID 36172373, 2022). "Increasing studies have revealed that the cGAS–STING pathway plays a significant role in the development of neurodegenerative diseases." (PMID 36618820, 2022). "Accumulating evidence has indicated the cGAS-STING pathway in driving neuroinflammation of neurodegenerative diseases, thus inhibition of this pathway represents a viable therapeutic in the treatment of neurodegenerative diseases." (PMID 35741054, 2022). "Excessively accumulated cytosolic DNA acts as a damage-associated molecular pattern (DAMP) that is monitored by the cGAS-STING axis to trigger the immune response in many degenerative diseases." (PMID 35145201, 2022). "As with other neurodegenerative disease–associated protein aggregates, α Syn fibrils can elicit cGAS/STING assembly.α Syn-PFF–injected mice upregulated γH2AX (an indicator of nuclear dsDNA damage), cGAS, STING, and pTBK1 as well as STING-dependent IFNβ levels." (PMID 41386298, 2025). "In addition to neurodegenerative diseases, inhibition of the cGAS/STING/NLRP3 signaling pathway can also improve neonatal hypoxic-ischemic encephalopathy and cerebral venous sinus thrombosis." (PMID 40463371, 2025). "A more refined mechanistic understanding of how DNA ligands, including mitochondrial DNA, trigger cGAS in autoinflammatory, autoimmune, and degenerative diseases may further inform therapeutic modulation strategies upstream of cGAS." (PMID 39295301, 2024). "However, there is limited work demonstrating the activation of the cGAS-STING pathway in human neurodegenerative diseases." (PMID 37239045, 2023). "In addition to neurodegenerative diseases and cardiovascular diseases, the cGAS/STING/NLRP3 signaling pathway is involved in the pathological process of acute pancreatitis, mastitis, acute kidney injury, acute liver injury, acute lung injury, systemic lupus erythematosus, and allergic rhinitis." (PMID 40463371, 2025). "Targeting cGAS might be a promising anti-senescence strategy for IVD degenerative disease." (PMID 39034400, 2024). "As mechanistic studies continue to uncover novel pathogenic mediators within the cGAS-STING-IFN-I signaling pathway, diverse drug targets will likely be explored in the years to come, offering hope for the development of effective treatments for neurodegenerative diseases." (PMID 38774266, 2024). "Single-cell transcriptional profiling of cGAS gain-of-function mice further reveals that, beyond type I IFNs, cGAS activation alone triggers a core microglial gene expression program that is shared between many neurodegenerative disease states and during ageing." (PMID 37532932, 2023). "Second, the long‐term impact of targeting LINE‐1 or cGAS‐STING pathways on systemic aging and neurodegenerative diseases, such as AD and PD, should be explored." (PMID 41480826, 2026). "The cytosolic DNA sensing pathway, involving cGAMP synthase (cGAS) and Stimulator of Interferon Genes (STING), has emerged as a key mediator of neurodegenerative diseases." (PMID 39908354, 2025).
neurodegenerative disease (continued). "The mitochondrial DNA released by stress has a sustained activation effect on the cGAS STING pathway, and mitochondrial damage (BAX/VDAC pore) releases oxidized mtDNA, mediating neurodegenerative diseases such as Parkinson’s disease." (PMID 41007720, 2025). "More and more studies have found that the cGAS/STING signaling pathway plays an important role in infectious diseases, neurodegenerative diseases, autoimmune diseases, inflammatory diseases, liver diseases, cardiovascular diseases, and tumors." (PMID 40463371, 2025). "mtDNA mislocalization and its cytopasmatic accumulation can trigger inflammation via the cyclic cGAS-STING pathway, observed in many neurodegenerative diseases." (PMID 40943287, 2025). "The cGAS–STING pathway has been identified as a potential contributor to a range of neurological disorders, including neurodegenerative diseases and CNS injury." (PMID 41041519, 2025). "The cGAS-STING innate immunity pathway and the SREBP-activated cholesterol and fatty acid synthesis pathway are abnormally co-regulated in neurodegenerative disease." (PMID 39156128, 2024). "In recent years, the cyclic GMP-AMP synthase (c-GAS)-stimulator of interferon genes (STING) signaling pathway, has been increasingly regarded as an important regulator in neuro-immunological and neurodegenerative disease, in addition to neuro-oncology." (PMID 39555096, 2024). "For instance, studies have revealed the crosstalk between cGAS-STING and autophagy and lipid metabolism pathways, both of which are highly dysregulated in neurodegenerative diseases." (PMID 37941028, 2023). "Research interest has been growing in the role of cGAS-STING in the CNS, as neuroinflammation has proved to be a key player in neurological and neurodegenerative diseases." (PMID 37941028, 2023). "Collectively, inhibiting the cGAS-STING pathway and its related signaling molecules presents a promising therapeutic approach for the treatment of neurodegenerative diseases." (PMID 38069505, 2023). "Beyond its involvement in host defense, the cGAS-STING signaling has been found to play a role in various physiological and pathological processes, including anti-tumor immunity, neurodegenerative diseases, and inflammatory diseases." (PMID 38069505, 2023). "The innate inflammatory cGAS/STING pathway plays a pivotal role in metabolic dysfunction and is an emerging target of interest in multiple neurodegenerative diseases, including AD/ADRD." (PMID 37206668, 2023). "Cyclic GMP-AMP Synthase (cGAS) and Stimulator of Interferon Genes (STING) also play a role in the induction of IFN-I following CNS injury and during neurodegenerative disease." (PMID 34504493, 2021). "The cGAS/STING pathway plays a unique and critical role in neuroinflammation and neurodegenerative diseases as one of the important aberrant cytoplasmic DNA monitors." (PMID 34943020, 2021). "The present study hypothesized that the dysregulated activation of cGAS-STING signal routing is involved in many autoinflammatory diseases, autoimmune diseases, and neurodegenerative diseases." (PMID 41007720, 2025). "While most studies have focused on neurodegenerative diseases, a few emerging reports indicate that SCI‐induced tissue damage may trigger the release of cytosolic DNA, thereby activating the cGAS‐STING pathway." (PMID 40522023, 2025). "The cGAS-STING pathway, integral to innate immune responses, may contribute to the chronic neuroinflammation seen in neurodegenerative diseases." (PMID 41300248, 2025). "It is worth noting that, as of now, no cGAS inhibitor has entered clinical trials to assess their effects on neurodegenerative diseases or other conditions." (PMID 37941028, 2023). "Therefore, targeting the cGAS‐STING signaling pathway highlights the potential for broad‐therapeutic treatment of antiviral‐induced neuroinflammation in PD and other neurodegenerative diseases." (PMID 36914567, 2023).